CGAS (cyclic GMP-AMP synthase)
Diseases named in the same sentence as CGAS in open-access papers (continued):
Sharing a sentence is not in itself a finding about the gene and the disease.
systemic lupus erythematosus (continued). "Additionally, cGAS activation by self-DNA has been indicated in Sting–/–DNaseII–/– and cGAS–/–DNaseII–/– models with reduced lupus-like manifestations." (PMID 36719379, 2023). "cGAS or STING elimination in different models of lupus, in which CD95/Fas has been involved, also suggests that these factors could protect from the pathology progression." (PMID 35563744, 2022). "Therefore, the controversial role of the cGAS/STING signaling pathway in the lupus mouse model suggests that further study of the mechanism is needed to verify a potential new therapeutic target for SLE patients." (PMID 36591278, 2022). "It is suggested that cGAS-STING also contributed to the adaptive immune response in lupus." (PMID 34718330, 2021). "cGAS deficiency also increases the expression of the caspase-11 gene, leading to activation of the caspase-11 non-canonical inflammasome in the lungs of pristane-induced lupus mice." (PMID 38396768, 2024). "Studies have illustrated that Aicardi-Goutières syndrome (AGS) and systemic lupus erythematosus (SLE) are all resulted from systemic activation of cGAS–STING signal axis." (PMID 35871231, 2023). "Similarly, in systemic lupus erythematosus (SLE) hyperactivation of cGAS-STING signaling in T cells also required suppression of Ca2+ homeostasis, but whether STIM1 was involved is not clear." (PMID 36139387, 2022). "DNA in apoptotic bodies is abundant in systemic lupus erythematosus (SLE) serum that facilitates ISG expression via the cGAS–STING pathway." (PMID 35084490, 2022). "Systemic lupus erythematosus (SLE) development is classically linked to endosomal toll like receptor (TLR) 7 and TLR9 nucleic acid sensors engagement and the role of the cGAS/STING pathway remains elusive." (PMID 34659260, 2021). "cGAS-mediated inflammation has been recognized to be at the root of a multitude of diseases, ranging from systemic rheumatological conditions, including rheumatoid arthritis (RA) and systemic lupus erythematosus (SLE), to organ-specific pathologies such as myocardial infarction (MI)." (PMID 32774773, 2020). "Therefore, keeping cGAS-STING function in line could be a potential therapeutic strategy for the diseases caused by reduced TREX1 activity, such as lupus." (PMID 32180716, 2020). "The cGAS-STING pathway is emerging as an essential driver in systemic lupus erythematosus (SLE)." (PMID 41773721, 2026). "The transcriptomic expression profile of these receptors and ectoenzymes seemed to be coordinately expressed with genes of cGAS-STING signaling pathway and a number of interferon stimulated genes, two hallmarks in the lupus pathology." (PMID 39995666, 2025). "Research has shown that IFIT3 is significantly elevated in monocytes from systemic lupus erythematosus (SLE) patients, where it is positively correlated with cGAS-STING pathway activity, highlighting its role in amplifying antiviral responses." (PMID 40061935, 2025). "In this context, the cGAS‐STING inhibitory peptide ISD017, which has shown anti‐inflammatory effects in preclinical lupus models, warrants investigation for its potential to mitigate muscle wasting." (PMID 41231146, 2025). "Thus, this form of mtDNA and cGAS–STING activation may be involved in lupus pathology." (PMID 37001140, 2023). "Oxidized mtDNA released by NETosis in human lupus promotes autoimmunity and type I IFN signatures via activating the cGAS‒STING pathway." (PMID 35084490, 2022). "By sensing dsDNA, the cGAS-STING pathway has become a key pathway in autoimmune and inflammatory diseases, such as Sjogren’s syndrome, systemic lupus erythematosus (SLE), and multiple sclerosis." (PMID 35812407, 2022). "Most cells contain DNA, so the cGAS-STING pathway plays a role in many inflammatory diseases, including acute pancreatitis, sepsis, colitis, systemic lupus erythematosus, Sjogren's syndrome, and autoimmune encephalomyelitis 37,38,43-46." (PMID 35280696, 2022).
systemic lupus erythematosus (continued). "In addition, increased cGAS mRNA levels and production of cGAMP have been observed in Systemic Lupus Erythematosus (SLE) patients, indicating that cGAS-STING signaling is also involved in a subset of SLE patients." (PMID 33968056, 2021). "Systemic lupus erythematosus (SLE) neutrophils release mtDNA, which activates the cGAS-STING pathway to promote type I IFN-regulated autoimmunity." (PMID 34016129, 2021). "The E3 ligase RNF185, expression of which is upregulated in Systemic Lupus Erythematosus (SLE) patients, has been shown to be involved in the regulation of cGAS activity." (PMID 29546673, 2018). "For example, both MDA5 and cGAS were upregulated in in vitro maturated splenic B cells from a TLR7 agonist-induced lupus model, while the MDA5 pathway was also activated without additional stimulation with CD40L." (PMID 38791389, 2024). "cGAS, a member of the PRR family, recognizes endogenous and exogenous DNA, activates innate immunity, and affects numerous autoimmune diseases such as SAVI, Systemic lupus erythematosus (SLE), and Aicardi-Goutières syndrome (AGS)." (PMID 37965345, 2023). "Since cGAS is a key mediator in the effects of UV light, exploration of the mechanisms of the cGAS-STING pathway will lead us to better understanding of photosensitivity in lupus." (PMID 36091671, 2022). "Although the expression of cyclic GMP-AMP, DNA-activated cGAS-STING pathway, activated IFN-I, and increased in a proportion of patients with SLE, the data from lupus mouse models reveal the differential roles of STING in lupus pathogenesis depending on the models." (PMID 33083760, 2020). "Hyperactivation of the cGAS-STING pathway contributes to autoimmune illnesses, including rheumatoid arthritis (RA), systemic lupus erythematosus (SLE), and Aicardi-Goutieres syndrome (AGS), as well as other conditions such as cancer." (PMID 40028324, 2025). "Here, we found that PIL induced severe lupus activity without cGAS." (PMID 36591278, 2022). "Similarly, excess nucleic acids in lupus are thought to lead to enhanced cGAS-STING signaling, although this is not an exclusive nucleic acid sensing pathway in this highly heterogenous disease." (PMID 35693769, 2022). "The absence of cGAS leads to the rise of cytosolic dsDNA, accelerates noncanonical inflammasome activation in macrophages, and aggravates lupus pathology in the pristane-induced lupus model." (PMID 36591278, 2022). "While the cGAS-STING pathway is critical for antimicrobial defense, its activation by self-DNA can also lead to autoimmune conditions such as systemic lupus erythematosus (SLE) and rheumatoid arthritis." (PMID 39669992, 2024). "Longer DNA fragments stimulate cGAS mediated IFN-I production more efficiently and bind with higher affinity to dsDNA autoantibodies that accumulate in autoimmune syndromes such as systemic lupus erythematosus (SLE)." (PMID 33717156, 2021). "However, the contribution of the cGAS-STING pathway, relative to endosomal TLRs, in systemic lupus erythematosus (SLE) is controversial." (PMID 33854495, 2021). "Thus, DNA sensing through cGAS-STING has emerged as a triggering factor in the pathogenesis of type I interferonopathies and self-DNA inflammatory diseases, such as Aicardi-Goutières syndrome or systemic lupus erythematosus, and also with implications in cancer immunosurveillance." (PMID 32948585, 2020). "Our findings are overall in line with a recent study reporting that the cGAS-STING pathway does not promote autoimmunity in two murine models of SLE, the pristane induced lupus model and the genetically programmed MRL/lpr model." (PMID 34938294, 2021). "Whether exclusively cGAS and STING are induced after UV irradiation in lupus is currently not clear." (PMID 36091671, 2022).
Autoimmunity (74 papers, 2017 to 2026). The occurrence of an immune reaction against the organism's own cells or tissues. "In the realm of cGAS inhibitors, the first mechanism focuses on the post-translational modifications of cGAS, with Aspirin being an example that targets cGAS acetylation at Lys 384/394/414 to effectively suppress autoimmunity caused by TREX1 genetic deletion." (PMID 38803502, 2024). "In contrast, our study shows that cGAS in macrophages was dispensable for autoimmunity caused by TREX1 deficiency." (PMID 39254994, 2024). "Here, we report that patients with myotonic dystrophy have an increased prevalence of concomitant autoimmunity associated with a cGAS/STING-dependent activation of the type I IFN response." (PMID 38378748, 2024). "Considering that cGas-Sting axis mediates autoimmune phenotypes in Trex1−/− mice, we investigated the roles of Irf8 in autoimmunity in Trex1-deficient mice." (PMID 35973990, 2022). "One prominent example is that genetic KO of cGAS reverses the autoimmunity-related phenotype in a Trex1-deficient Aicardi–Goutieres Syndrome mouse model." (PMID 33273464, 2020). "However, in this study, we focused more on the cause of autoimmunity, and we also successfully identified a major cause of cGAS activation." (PMID 37786436, 2023). "Moreover, while loss of only one allele of cGAS was sufficient to ameliorate autoimmunity/cardiomyopathy in Trex1 knockout mice, knockout of both cGAS alleles was needed to prevent polyarthritis in DNase III knockout mice." (PMID 28679751, 2017). "Taken together, DNA damage and/or gene mutations in DNA/cGAS restriction factors under various disease conditions activate cGAS signaling in both the cytoplasm and nucleus upon DNA binding, which induces cGAS-dependent autoimmunity and exacerbates cGAS-associated sterile inflammation." (PMID 35084490, 2022). "Cytosolic mitochondrial DNA can then activate proinflammatory signaling pathways, mediated by TLR9 and cGAS, as well as inflammasomes, triggering inflammation and autoimmunity." (PMID 41011480, 2025). "The cGAS‐STING pathway is a classic autoimmunity pathway that is activate in presence of cytosolic DNA." (PMID 39921259, 2025). "MARCH8 negatively regulates the cGAS-mediated natural immune signaling pathway, and ARIH1 promotes antiviral and autoimmunity responses by catalyzing mono-ISGylation and cGAS oligomerization." (PMID 40028324, 2025). "Apoptosis/NETs DNA breaks through the DNase II/LAP degradation barrier and activates cGAS, driving autoimmunity such as SLE." (PMID 41007720, 2025). "Detection of cytosolic DNA by the cyclic GMP-AMP (cGAMP) synthase (cGAS)–stimulator of interferon genes (STING) pathway provides immune defense against pathogens and cancer but can also cause autoimmunity when overactivated." (PMID 39254994, 2024). "Increasing research suggests that the cGAS-STING pathway plays an important role in the development of many diseases through its involvement in autoimmunity, cellular senescence and anti-inflammation." (PMID 39113033, 2024). "This reversible modulation underscores the importance of phosphorylation as a means to control cGAS activity based on cellular context, ensuring that immune responses are both timely and appropriately restrained to avoid autoimmunity." (PMID 39669992, 2024). "In conclusion, NETs-DNA promotes NF-κB-dependent autoimmunity via cGAS/TLR9 in long-term CS exposure-induced COPD." (PMID 38880789, 2024). "Cyclic GMP-AMP (cGAMP) synthase (cGAS) has been shown to mediate this autoimmunity by detecting cytosolic DNA, and inhibitors targeting the cGAS pathway reduce inflammation and disease phenotypes in Trex1–/– mice." (PMID 39254994, 2024). "This mtDNA is, in turn, sensed by the cGAS/STING pathway and induces a type-I IFN response predisposing to autoimmunity." (PMID 38378748, 2024).
Autoimmunity (continued). "Elevated levels of cytoplasmic DNA due to inflammation, autoimmunity, tumors, bacteria and viruses would lead to constitutive and systemic activation of cGAS-STING and promote the body’s immune defense." (PMID 37153576, 2023). "In contrast, a recent study demonstrated that STING and cGAS deficiencies exacerbate disease symptoms in a chronic model of 2,6,10,14-tetramethylpentadecane (TMPD)-induced autoimmunity." (PMID 37354378, 2023). "cGAS/STING is positioned as a key axis of autoimmunity, the inflammatory response, and cancer progression, suggesting that the cGAS/STING signaling pathway represents an efficient therapeutic target." (PMID 37354378, 2023). "Here, we show that ariadne RBR E3 ubiquitin protein ligase 1 (ARIH1) catalyzes the mono-ISGylation and induces the oligomerization of cGAS, thereby promoting antiviral immunity and autoimmunity." (PMID 36217001, 2022). "The cytosolic DNA sensor cyclic GMP-AMP synthase (cGAS) plays a critical role in antiviral immunity and autoimmunity." (PMID 36217001, 2022). "Collectively, these findings reveal a previously uncharacterized posttranslational modification of cGAS that promotes optimal activation of cGAS and cGAS-mediated antiviral immunity and autoimmunity." (PMID 36217001, 2022). "By using Trex1−/− mice, a mouse model of human Aicardi-Goutieres Syndrome and SLE, the importance of the cGAS signaling in autoimmunity has been well demonstrated." (PMID 34819357, 2022). "The activity and stability of the cytosolic DNA sensor cGAS, a key mediator of innate antiviral immunity and autoimmunity, is fine-tuned by post-translational modifications." (PMID 36217001, 2022). "Previous studies in mouse models with defective DNA clearance revealed a critical role for the cGAS–STING pathway in mediating autoimmunity." (PMID 34901991, 2022). "Consistent with this premise, mice lacking cGAS and Unc93B1 or STING and Unc93B1 developed minimal systemic autoimmunity as compared to cGAS or STING single knock out animals." (PMID 33854495, 2021). "To assess the possibility of miR-23a/b for the treatment of cGAS-mediated autoimmunity, we first transfected miR-23a/b mimics or control mimics into BMDMs isolated from WT and Trex1−/− mice." (PMID 33767433, 2021). "Cells must stringently regulate cGAS activity in order to mount a robust immune defense against infections while avoiding autoimmunity." (PMID 33542149, 2021). "Precise activation and tight regulation of cGAS are vital in appropriate innate immune responses, senescence, tumorigenesis and immunotherapy, and autoimmunity." (PMID 32195086, 2020). "The importance of cGAS-STING signaling in autoimmunity has been highlighted by genetic studies of human patients with other autoimmune diseases." (PMID 33273464, 2020). "This study provides a rational explanation for the autoimmunity of patients with missense mutations of PRKDC, and suggests that cGAS-mediated immune signaling is a potential target for therapeutic interventions." (PMID 33273464, 2020). "This contributes to keeping cGAS inactive, and robustly suppresses self-DNA-induced autoimmunity through the STING pathway." (PMID 32574107, 2020). "Our study also provides a rational explanation for the autoimmunity phenotype observed in patients with PRKDC mutations, suggesting that the cGAS-mediated immune signaling is a potential target for therapeutic interventions." (PMID 33273464, 2020). "cGAS is essential for the host defense against numerous pathogens, regulates tumorigenesis, and is involved in autoimmunity." (PMID 32170294, 2020). "Recently, cGAS acetylation and inhibition by aspirin has been shown to effectively suppress DNA-mediated autoimmunity in Aicardi–Goutieres patient cells." (PMID 33273464, 2020). "Recent studies showed that the deletion of cGAS fully rescued the self-DNA-induced autoimmunity, suggesting that inhibition of chronic activation of cGAS is critical for treating these diseases." (PMID 29760876, 2018).
Autoimmunity (continued). "Recent studies have suggested that TREX1 suppresses the activation of the endogenous DNA sensor cGAS and prevents autoimmunity by reducing cytosolic DNA, especially retroelement DNA." (PMID 28334850, 2017). "Additionally, aspirin acetylates cGAS at Lys384, Lys394, or Lys414, and its administration at 50 mg/kg mitigates autoimmunity in models of Aicardi-Goutieres syndrome and in patient-derived peripheral blood mononuclear cells." (PMID 40860203, 2025). "In conclusion we propose that chronic ER stress mediated by ATF6 activation allows cell survival at the expense of minority MOMP-mediated mtDNA release, leading to the activation of the cGAS/STING pathway and type I IFN-stimulated gene induction predisposing to autoimmunity." (PMID 38378748, 2024). "With increasing researches on cGAS and STING, the cGAS-STING pathway has been revealed to be involved in autoimmunity, cellular senescence and inflammation inhibition, indicating that it plays an important role in the occurrence of inflammation and many diseases.." (PMID 39113033, 2024). "TREX1 regulates the cGAS immune sensing pathway by reducing the cytosolic DNA level; thus, the loss-of-function of TREX1 causes overactivation of cGAS by endogenous DNA and leads to autoimmunity." (PMID 39254994, 2024). "Since TREX1 degrades DNA in the cytosol whereas DNase II degrades DNA in the lysosome, the type of cells driving autoimmunity via cGAS activation may depend on the subcellular localization of self-DNA." (PMID 39254994, 2024). "Despite a wealth of literature on the role of cGAS-STING signaling in autoimmunity and antimicrobial immunity, there are numerous open questions about the biochemistry, cell biology, and regulatory mechanisms associated with STING signaling and STING-mediated immunity." (PMID 37247757, 2023). "On the other hand, overactivation of cGAS-STING signal may cause severe inflammatory pathologies including autoinflammation and autoimmunity." (PMID 35871231, 2023). "Therefore, elucidating the regulatory mechanisms for cGAS activation would provide insight into the understanding of antiviral immunity and autoimmunity." (PMID 36217001, 2022). "Whether and how cGAS undergoes ISGylation to regulate antiviral immunity and autoimmunity are completely unknown." (PMID 36217001, 2022). "High-affinity nucleosome binding blocks genomic DNA binding and prevents cGAS-induced autoimmunity." (PMID 35084490, 2022). "Our results may explain how bacterial LPS can synergize with cGAS-pathway in promoting the development of SLE-like autoimmunity." (PMID 33916318, 2021). "Inappropriate activation of cGAS by self-DNA promotes severe autoinflammatory diseases such as Aicardi–Goutières syndrome (AGS); thus, inhibition of cGAS may provide therapeutic benefit in anti-autoimmunity." (PMID 33968056, 2021). "TREX1 dysfunction activates the cGAS-STING DNA-sensing pathway resulting in autoimmunity." (PMID 33868310, 2021). "Other pathological modifications to the cGAS-STING pathway, such as mutations of the exonuclease Trex1, have been linked to several other autoimmune conditions, including Aicardi-Goutières syndrome (AGS), SLE, familial chilblain lupus and retinal vasculopathy with cerebral leukodystrophy (RVCL)." (PMID 32774773, 2020). "Indeed, aspirin keeps cGAS inactive, and robustly suppresses self-DNA-induced autoimmunity through the STING pathway." (PMID 32574107, 2020). "Chronic activation of cGAS-STING by auto-DNA may lead to autoimmunity." (PMID 41007720, 2025). "cGAS may be activated by either endogenous DNA, mitochondrially-released DNA, or genotoxic stress-mediated extranuclear chromatin, placing cGAS-STING as a crucial signaling axis in autoimmunity, the sterile inflammatory response, and the induction of cellular senescence." (PMID 40552295, 2025).